EGR1 (early growth response 1)
Diseases named in the same sentence as EGR1 in open-access papers (continued):
Sharing a sentence is not in itself a finding about the gene and the disease.
liver fibrosis (17 papers, 2012 to 2026). "CEP72 deficiency accelerates the progression of liver fibrosis through the EGR1-TNF-α signaling pathway." (PMID 42087233, 2026). "Several secreted or intracellular factors related to cell regulation (“signaling pathway”) were also upregulated, some of them (Trib3, CTGF/CCN2, Egr1, Stat3...) having been linked to inflammation, tissue repair, liver fibrosis and TGFβ signaling." (PMID 26446156, 2016). "Previous research has shown that EGR1 is involved in liver fibrosis progression downstream of Elk-3 in CCl4-induced mouse liver fibrotic tissues and human liver cirrhotic tissues." (PMID 40393967, 2025). "In conclusion, the evidence collected revealed that MMF effectively enhanced the architecture of the fibrotic liver and ameliorated the biochemical indicators of liver fibrosis by inhibiting Egr-1." (PMID 40526279, 2025). "In fact, EGR1 expression was well correlated with the progression or regression of liver fibrosis in our cohort of serial biopsied MASH liver samples (data not shown)." (PMID 38619434, 2024). "Egr-1 is a proinflammatory nuclear transcription factor; Egr-1 knockout mice were shown to exhibit more severe liver fibrosis, which was induced by treatment with acetaminophen (APAP)." (PMID 33880382, 2021). "Deletion of EGR1 exacerbated liver fibrosis of long-term acetaminophen-induced hepatotoxicity in mice." (PMID 34683877, 2021). "EGR-1 has been reported to be a negative regulator of hepatic fibrosis mediated by the environmental pollutant and liver toxicant, carbon tetrachloride." (PMID 33250767, 2020). "Egr1 has been shown to contribute to liver fibrosis progression downstream of Elk-3 in CCl4-induced mouse liver fibrotic tissues and human liver cirrhotic tissues." (PMID 32121305, 2020). "Research efforts using various animal models such as fatty liver, liver injury, and liver fibrosis contribute greatly to the elucidation of Egr1 function in the liver." (PMID 29607419, 2017). "Egr1 also controls the expression of a number of inflammatory mediators contributing to liver fibrosis." (PMID 22811744, 2012). "Additionally, an upregulation of EGR1 expression was observed in CCl4-induced mice, suggesting a potential link between EGR1 and the progression of liver fibrosis." (PMID 40393967, 2025). "In an acute acetaminophen-induced liver injury mouse model, the inhibition on ERK1/2-mediated Egr1 transcriptional activity attenuates hepatotoxicity, suggesting that inhibiting Egr1 is beneficial to protect against liver fibrosis observed in long-term application of acetaminophen." (PMID 32121305, 2020). "Collectively, these data support Egr1 as an important mediator in APAP-induced hepatotoxicity and liver fibrosis; however, whether Egr1 could act as an inducer or protector against APAP-induced liver injury has remained elusive." (PMID 29607419, 2017). "However, the beneficial effect of Egr1 deletion in the context of liver fibrosis is contradictory." (PMID 32121305, 2020). "The purpose of this investigation is to explore the molecular pathways that underpin radiation-induced hepatic fibrosis and to assess the potential influence of MMF on Egr-1 over radiation (IRR)-induced fibrogenesis in rats." (PMID 40526279, 2025). "As such, in the Bsep-/- CCl4 setting, Egr1 might not play a decisive role in counteracting development of hepatic fibrosis." (PMID 40946964, 2026). "First, TGF-β regulates p300 expression by Early Growth Response 1 (EGR1) and can regulate the translocation of p300 through posttranslational modification; for example, the phosphorylation of p300 by AKT signaling has been reported to induce its translocation to the nucleus in liver fibrosis." (PMID 36864460, 2023).
fibrosarcoma (16 papers, 2009 to 2023). A malignant mesenchymal fibroblastic neoplasm affecting the soft tissue and bone. "In a mouse fibrosarcoma model, anti-tumor and anti-angiogenesis effects were observed in response to injection of an adenovirus encoding Egr-1, but the gene was delivered to both tumor and stroma." (PMID 19200397, 2009). "Low expression levels of EGR1 are also found in other tumor types, including breast, lung, and fibrosarcoma." (PMID 36338037, 2022). "Following UV irradiation in a fibrosarcoma model, EGR1 is phosphorylated by both protein kinase C (PKC) and tyrosine kinases and protects cells from apoptosis." (PMID 36338037, 2022). "Meanwhile, phosphorylation by casein kinase II in fibrosarcoma cells decreases the transcriptional activity of EGR1 as well as its DNA binding activity." (PMID 36338037, 2022). "UV irradiation activates Egr1 expression in multiple cell types, including mouse and human fibroblasts as well as human fibrosarcoma cells." (PMID 32121305, 2020). "Egr1 has been shown to induce transcription of growth factors and stimulate collagen production in human fibroblasts and fibrosarcoma cells, suggesting the contribution of Egr1 to fibrogenesis." (PMID 29607419, 2017). "By contrast, tumor suppressor activity of Egr1 was reported in fibrosarcoma, glioblastoma, lung and breast cancers." (PMID 29607419, 2017). "In HT-1080 fibrosarcoma cells, EGR-1 was found to suppress cell growth by activating TGF-beta 1 and in a recent study of synovial sarcoma, it was found to mediate cell death induced by HDAC inhibitor through activation of PTEN." (PMID 26573568, 2015). "In fibrosarcoma, UV exposure leads to EGR1 phosphorylation by PKC (protein kinase C) and tyrosine kinases, conferring on EGR1 a protective and anti-apoptotic function." (PMID 32121305, 2020).
cognitive deficits (15 papers, 2011 to 2025). "Both loss and gain of function manipulations to these activity-regulated genes, including Arc, Bdnf, Reln, Egr1 and Ppp3ca, have been associated with cognitive deficits during physiological aging and pathological conditions like dementia, neurodegenerative diseases and neuropsychiatric problems." (PMID 33013350, 2020). "Thus, Gsx induces an alteration of emotional reactivity and a memory/cognitive deficit that is associated with reduced turnover of serotonin and dopamine in the nucleus accumbens and decreased expression of Egr-1 in the hippocampus and amygdala." (PMID 21535247, 2011). "It has been noted that the expression of EGR1 was significantly decreased in the hippocampal tissues of mice exposed to 14 days of chronic stress, accompanied by cognitive deficits." (PMID 41007965, 2025). "Research indicates that in Alzheimer’s disease model mice, EGR1 is downregulated when the mice display cognitive deficits." (PMID 39234114, 2024). "Since EGR1 inhibition was also shown to activate BACE1 activity, this calls for further studies into the role of (early life) modulation of EGR1 and its implication in cognitive impairment and AD neuropathology." (PMID 30227888, 2018). "A decline in Arc and Egr1 expression levels was correlated with the occurrence of cognitive impairment during aging and in transgenic mice carrying genes responsible for AD." (PMID 23125823, 2012). "Conversely, knockdown of EGR1 improved cognitive deficits in 3xTgAD mice." (PMID 36517890, 2022). "In this sense, the normalization of Crh, Crhr1, and Egr1 mRNA levels by social support may be involved in the stress-induced cognitive impairments." (PMID 30104581, 2018). "After a certain threshold has been reached, EGR1 is no longer able to compensate sufficiently given the synaptotoxic consequences of Aβ, and cognitive impairment associated with the symptomatic stage of AD is thought to commence." (PMID 30227888, 2018). "Moreover, prolonged B1R blockade enhanced the baseline levels of the memory-related Egr-1 protein in the DG, a brain region previously associated in APP mice with cognitive deficits, reduced immediate-early gene expression and altered synaptic activity." (PMID 23642031, 2013). "We found that DDW-exposed old mice displayed elevated expression of Egr1, the downregulation of which is related to MDD and stress, as well as cognitive deficits." (PMID 41226662, 2025).
Hyperglycemia (15 papers, 2013 to 2025). An increased concentration of glucose in the blood. "In this study, we performed in vivo and in vitro experiments and demonstrated that GPR43 deficiency decreased EGR1 protein expression in podocytes under hyperglycemia." (PMID 34975320, 2022). "Our results indicate that hyperglycemia induces SOD2 expression through decreased association of Egr1 on the SOD2 promoter." (PMID 31685635, 2019). "Images comparing EGR1 staining between normal and hyperglycemic groups reveal a qualitative reduction in signal intensity under hyperglycemia." (PMID 40855901, 2025). "Early growth response factor 1 (EGR1) is a zinc‐finger transcription factor induced by various stimuli including hypoxia, hyperglycemia, radiation, or chemotherapy." (PMID 40635521, 2025). "Egr-1 expression is triggered by a host of factors including cytokines, hormones, growth factors, hyperglycaemia, biomechanical forces and oxygen deprivation." (PMID 39619154, 2024). "It will be interesting to further understand the mechanism through which hyperglycemia interferes with Egr-1 upregulation during the process of arteriogenesis." (PMID 31284541, 2019). "Further investigation showed that hyperglycemia-induced SOD2 suppression is due to persistent oxidative stress-mediated histone methylation and the subsequent decreased association of Egr1 on the SOD2 promoter." (PMID 31685635, 2019). "In this study, we investigated the expression and regulatory mechanism of Egr1 in DR and found that Egr1 was augmented after the induction of hyperglycaemia." (PMID 30887692, 2019). "The results showed that both SOD2 (↑SOD2) and Egr1 (↑Egr1) lentivirus completely restored hyperglycemia-induced H3K9me2 modification and SOD2 suppression." (PMID 31685635, 2019). "On the contrary, hyperglycemia-induced persistent elevated ROS generation was completely diminished after infection of either SOD2 lentivirus (↑SOD2) or Egr1 lentivirus (↑Egr1)." (PMID 31685635, 2019). "Further investigations exploring the mechanism by which hyperglycemia suppresses Egr-1 expression during the process of arteriogenesis will lead to better understanding of impaired arteriogenesis in DM." (PMID 31284541, 2019). "We further analyzed EGR-1 contribution to hyperglycemia down-regulating GDNF-induced migration to HRPTE cells and GDNF-dependent phosphorylation of cRaf, MEK and ERK by small interfering RNA (siRNA) of EGR-1-mediated experiments." (PMID 23468876, 2013). "Our in vivo microarray, real time-PCR and confocal morphological observation confirmed apoptosis in hyperglycemia-induced fetal nephropathy via activation of the GDNF/MAPK/EGR-1 pathway at E12-E15." (PMID 23468876, 2013). "Despite these insights, the impact of hyperglycemia on the expression of EGR1, TLR4, and NF-κB in rotator cuff tendons remains unclear." (PMID 40855901, 2025). "In conclusion, this study demonstrates that hyperglycemia induces significant histological and molecular alterations in rotator cuff tendons, characterized by degenerative cellular changes and a pronounced upregulation of EGR1, TLR4, and NFκB transcripts." (PMID 40855901, 2025). "Additionally, EGR1 is verified to be upregulated in DR, and hyperglycemia-triggered EGR1 in the retinal endothelium upregulates the expression of downstream pro-thrombotic and pro-inflammatory genes." (PMID 34608841, 2021). "Moreover, sh‐Egr1 partially reduced the injurious effects of hyperglycaemia on retinal vascular function by decreasing apoptotic cells and microvascular formation in vivo." (PMID 30887692, 2019). "EGR-1 is also induced by a number of different stimuli, such as anti-cancer drugs, oxidized lipids, hyperglycemia, growth factors and ionizing radiation, and inhibits or stimulates tumor growth depending on the cellular context and the duration of EGR-1 induction." (PMID 28758926, 2017).
Hyperglycemia (continued). "To determine whether EGR-1 mRNA expression was up-regulated by hyperglycemia, we exposed HRPTE cells to GDNF in high glucose concentration." (PMID 23468876, 2013). "Our results indicate that hyperglycemia-induced SOD2 suppression in neurons is due to hyperglycemia-induced H3K9me2 histone methylation and the subsequent dissociation of Egr1 on the SOD2 promoter." (PMID 31685635, 2019). "We also found that hyperglycemia-induced SOD2 suppression is due to oxidative stress-mediated histone methylation with H3K9me2 and the subsequently decreased binding ability of Egr1 on the SOD2 promoter." (PMID 31685635, 2019). "Among them, EGR-1 has been demonstrated as a regulatory protein for GDNF and essential for tubulogenesis in hyperglycemia-induced renal embryopathy." (PMID 23468876, 2013). "Our data additionally revealed Nox4-induced ROS generation, hyperglycemia-induced mitochondrial dysfunction leading to reduced antioxidant capacity, NFAT5 overexpression, and glucose-induced upregulation of EGR1." (PMID 23149823, 2013). "Only a sustained increase in glucose flux-induced activation of Egr1 has been reported; however, the exact mechanism by which increased Egr1 activity is induced by hyperglycemia has not been fully investigated." (PMID 32626782, 2020).
lung adenocarcinoma (15 papers, 2014 to 2025). A carcinoma that arises from the lung and is characterized by the presence of malignant glandular epithelial cells. "Considering cancer suicide gene therapy for the treatment of lung adenocarcinoma, preclinical data support the use of resveratrol-responsive CArG domain elements [CC(A/T)6GG] from the Egr-1 promoter, in order to promote apoptosis and reduce the risk of metastasis." (PMID 27148534, 2016). "Consistent with our findings, the TCGA database analysis revealed the increase of miR-377-3p and the decrease of EGR1 in human lung adenocarcinoma tissues." (PMID 34497759, 2021). "This indicates that the inhibition of EGR1 mediates, at least in part, the less invasive phenotype caused by LINC-PINT in colorectal and lung adenocarcinoma cells." (PMID 29078818, 2017). "miR-183 belongs to one of the unique miRNAs in lung adenocarcinoma, and it has a potential oncogenic role in conjuction with two tumor suppressor genes, EGR1 and PTEN." (PMID 26170125, 2015). "Hypoxia/radiation dual sensitive chimeric HRE/early growth response 1 (Egr 1) promoter is a dual-targeting vector, which induces expression of the proapoptotic second mitochondria derived activator of caspases (Smac) gene in lung adenocarcinoma cells subjected to hypoxia and X ray irradiation." (PMID 28798809, 2017). "Based on TCGA and GTEx databases, the expression levels of FOS, GADD45B, and EGR1 in liver hepatocellular carcinoma (LIHC) and lung adenocarcinoma (LUAD) were lower than those in normal samples." (PMID 37405258, 2023). "Accordingly, EGR1, EGR2, and EGR3 were differentially expressed genes (DEGs) in several cancers, such as bladder urothelial carcinoma (BLCA), BRCA, and lung adenocarcinoma (LUAD)." (PMID 33614706, 2020). "By integrating two time-course microarray data in human lung adenocarcinoma cells, we specifically have identified some nested gene clusters and found that TGFB1, EGR1, EGR2, EGFR, IL6, JUN, and JUNB all are involved in these clusters." (PMID 28959347, 2017). "Moreover, TCGA database revealed that EGR1 in lung adenocarcinoma patients (LUAD) was significantly lower than in noncancerous tissue, and the downregulation level of EGR1 was associated with poor prognosis and short survival inversely." (PMID 34235076, 2021).
myocardial infarction (15 papers, 2014 to 2025). Gross necrosis of the myocardium, as a result of interruption of the blood supply to the area, as in coronary thrombosis. "Studies have shown that abnormal Egr-1 expression is linked to different animal and human disorders like heart failure and myocardial infarction." (PMID 37057102, 2023). "Post-myocardial infarction, exosomal miR-146a from transfected ADSCs directly suppressed early growth response factor 1 (EGR1) activation and IL-1β/-6 and TNF-α expression due to inhibition of the toll-like receptor 4 (TLR4)/NF-κB pathway." (PMID 40676634, 2025). "In another research study, EGR1 was regarded as a ferroptosis inducer in acute myocardial infarction because it inhibited GPX4 to promote ferroptosis via miR-15a-5p." (PMID 38397780, 2024). "Exosomes derived from miR-146a-modified ADSCs reduced acute myocardial infarction (AMI)-induced myocardial damage by downregulating early growth response factor 1 (EGR1)." (PMID 36901991, 2023). "Some rat model-based studies have shown that Egr-1 gene inhibition decreases the pathological effects of acute myocardial infarction (AMI)." (PMID 37057102, 2023). "The Egr-1 regulates ferroptosis in acute myocardial infarction through miR-15a-5p/GPX4 axis, while GPX4 regulated mitochondria-mediated apoptosis through regulation of Egr1 in TNBC cells." (PMID 36238640, 2022). "Published data have shown that EGR1 often acts as a transcription factor to activate downstream genes in the ischemic arrhythmia and myocardial infarction models induced by oxygen-glucose deprivation/reperfusion injury." (PMID 35126807, 2022). "Doxorubicin induced cardiomyopathy is also mediated by Egr-1 and targeting Egr-1 reduces the pathological effects of acute myocardial infarction in rats." (PMID 24451137, 2014). "In addition, the LDH and CK activity in arterial blood as well as myocardial infarct size and cardiomyocyte apoptosis was attenuated upon EGR1 silencing or TLR4/TRIF inhibition." (PMID 35126807, 2022). "Egr1 was induced in the early response to myocardial infarction (MI), and Egr1 governed expression of several downstream targets implicated in inflammation, thrombosis, and apoptosis following MI." (PMID 35625405, 2022). "In an acute myocardial infarction rat model produced by surgical ligation of the left anterior descending coronary artery, exosomes from miR-146a-ADSCs promoted myocardial cell apoptosis, inflammatory response, and fibrosis, and attenuated myocardial infarction by downregulating EGR1." (PMID 35884901, 2022). "Artesunate was also reported to activate the PI3K/Akt pathway in rodent models of subarachnoid hemorrhage and myocardial infarction, and the PI3K/Akt pathway has also been shown to control EGR1 expression." (PMID 36707892, 2023). "Gain- and loss-of-function experiments were performed to evaluate the effect of the circ_SMG6/miR-138-5p/EGR1/TLR4/TRIF axis on cardiac functions, myocardial infarction, myocardial enzyme levels, cardiomyocyte activities, and neutrophil recruitment." (PMID 35126807, 2022). "Similarly, suppressed EGR1 expression is capable of disrupting hypoxia-induced TLR4/NF-κB signaling pathway activation, which can facilitate acute myocardial infarction-induced myocardial damage." (PMID 35126807, 2022).